MTOR (mechanistic target of rapamycin kinase)
Diseases named in the same sentence as MTOR in open-access papers (continued):
Sharing a sentence is not in itself a finding about the gene and the disease.
tumor (continued). "Cadherin 1 (CDH1) gene encoding E-cadherin protein that is responsible for cell–cell adhesion, is a tumor suppressor gene related to the PI3/Akt/mTOR pathway and widely researched in BC with the evidence that downregulation is associated with poor prognostic parameters." (PMID 34679042, 2021). "Inhibition of mTOR was shown to effectively suppress tumor growth in CRC." (PMID 33946531, 2021). "It has been described that PI3K/AKT/mTOR axis drives EMT to promote tumor metastasis." (PMID 34459127, 2021). "In addition, the potential mechanism of the signature was revealed via GSEA, which showed that the biomarkers are involved in the mTOR signalling pathway in tumour progression." (PMID 34876138, 2021). "In vivo and in vitro experiments confirmed that quercetin downregulated the expression of cell migration marker proteins and inhibited the glycolysis process by decreasing the acidity of the tumor microenvironment, which were induced by Akt-mTOR pathway-mediated autophagy." (PMID 33494431, 2021). "In addition to its role in metabolism, AMPK also inhibits mammalian target of rapamycin (mTOR) pathway, which is hyper-activated in most tumor cells and plays a role in tumor progression." (PMID 34944514, 2021). "Additionally, miR-7-5p has been reported to regulate the epidermal growth factor receptor (EGFR) and EGFR/phosphatidylinositol 3-kinase/protein kinase B/mechanistic target of rapamycin (PI3K/Akt/mTOR) signaling pathway to affect tumor cell growth." (PMID 33768139, 2021). "In addition, Western blotting analysis of the tumor samples showed that lomerizine 2HCl can significantly downregulate the PI3K/AKT/mTOR signaling pathway in HT‐29 xenografts." (PMID 34766155, 2021). "Furthermore, heparin-binding factor midkine, secreted by tumour cells, facilitates lymphangiogenesis through paracrine activation of the mTOR signalling pathway in LECs, thus promoting metastasis progression." (PMID 35006432, 2021). "MiR-100 reduces the protein level of angiopoietin 2 (Angpt2) by targeting mTOR and blocking the mTOR-p70S6K signaling pathway, which in turn inhibits the formation of encapsulated tumor clusters (VETC), thereby eliminating VETC-dependent metastasis of HCC cells." (PMID 34123955, 2021). "The combination of the anti-IGF1R mAb h7C10 and the mTOR inhibitor rapamycin significanlty inhibited in vivo xenograft tumor growth, preventing tumor escape observed after the anti-IGF1R mAb h7C10 treatment alone and limiting the potential problem of mTOR inhibitors-evoked up-regulation of AKT." (PMID 34440844, 2021). "Also, it is showed that the PI3K/AKT/mTOR pathway is activated in GC with overexpression in tumor tissue, which is correlated with the depth of tumor infiltration and the presence of lymph node metastases." (PMID 35082831, 2021). "The mTOR blockade, therefore, interferes at multiple levels with tumor growth, and the dual targeting of EGFR and mTOR may have a greater effect with respect to the administration of a single target." (PMID 34769263, 2021). "However, the pro-apoptotic effect triggers autophagy as an escape pathway, counteracting the anti-tumor effect of mTOR inhibitors and contributing to resistance to these agents." (PMID 33467481, 2021). "Considering the critical role that mTOR signaling pathway plays in multiple tumor types, this novel discovery prompted us to wonder whether a similar mechanism exists in LUAD when RPS4X is activated by upstream molecules, like GTF2E2." (PMID 33757492, 2021). "The PI3K/AKT/mTOR (PAM) pathway is a key regulator of tumor therapy resistance." (PMID 34407844, 2021). "Furthermore, Akt-mTOR inactivation was detected in PCK1 shRNA-expressing PANC-1 xenograft tumor tissues." (PMID 34620839, 2021). "Targeting mTOR with specific inhibitors therefore results in autophagy induction, which might lay the foundation to the hypothesis of autophagy functioning as a tumour suppressor mechanism within this context." (PMID 33803216, 2021).
tumor (continued). "Inhibition of the mTOR pathway can inhibit tumor progression at multiple levels." (PMID 34863080, 2021). "For example, dying or necrotic tumor cells release high-[K+]e, which induces the inhibition of TCR-mediated Akt and mTOR phosphorylation and upregulates inhibitory protein PD-1 which, resulting in profound effects on tumor-resident T cell metabolic pathway and induces T cell suppression." (PMID 35250965, 2021). "Therefore, drugs targeting PI3K or mTOR in clinical trials can effectively reduce tumor growth, and the combination treatment with radiation can improve anticancer activity." (PMID 33471836, 2021). "In addition, hypoxia will also cause alterations of PI3 K/AKT/mTOR, MAPK, and NF‐ĸB pathways, thus promoting tumor metastasis." (PMID 33336932, 2021). "Overall, disparate expression of mTOR and ERK-1/2 associated signaling proteins can be selectively targeted along with mTOR or ERK-1/2 inhibitors to efficiently inhibit the tumor growth, metastasis, and to increase the overall survival depending upon the specific race." (PMID 33996789, 2021). "Similarly, treating gastrointestinal stromal tumor cells with Imatinib resulted in a reduction in mTOR signaling and stimulation of entry into dormancy." (PMID 34832087, 2021). "While p-mTOR expression was stable in both malignant and adjacent non-tumor tissues (P = 0.894)." (PMID 34458019, 2021). "Overall, PRMT5 may act as a tumor-inducing agent in ESCC by modulating LKB1/AMPK/mTOR pathway signaling." (PMID 34124017, 2021). "used API-2 (triciribidine, an AKT inhibitor) and RAD-001 (everolimus, a mTOR inhibitor) to target the PI3K/AKT/mTOR pathway and discovered that the inhibition of cell viability and proliferation in B7-H3 knockdown tumor cells was enhanced relative to that in their counterparts." (PMID 34349762, 2021). "In addition, the phosphatidylinositol 3-kinase/Akt/mTOR signalling pathway plays an important role in tumour cell proliferation, apoptosis, autophagy, relapse and metastasis, as well as the degradation of the extracellular matrix." (PMID 34495871, 2021). "More importantly, we recapitulated the impact of S3 on mTOR signalling in our tumour PDE system." (PMID 34382934, 2021). "The enhanced activation of mTOR signaling in the tumors promotes tumor radioresistance." (PMID 33959512, 2021). "Aberrant activation of the mTOR pathway is crucial for tumor cell growth and proliferation." (PMID 35071023, 2021). "PI3/AKT/mTOR signaling pathway is a very potential signaling pathway in tumor therapy." (PMID 34203270, 2021). "Interestingly, we observed a reduction in tumor microvessel density upon mTOR inhibition, which has been reported in other tumor models." (PMID 33479203, 2021). "Besides, p-PI3K/AKT/mTOR phosphorylation in vivo tumor tissues were also decreased in BI853520 treatment group than that in the control group." (PMID 35201437, 2021). "mTOR inhibitors have been tested against tumor cells with promising results." (PMID 33413302, 2021). "The suppression of mTOR is key for the antitumor effect in several tumor models." (PMID 34066940, 2021). "Therefore, LDN can be used as an adjuvant of clinical anti-tumor drugs in inhibiting the PI3K/AKT/mTOR signaling pathway, with high safety and low price." (PMID 33540155, 2021). "Thus, we conjecture that LQ exerted anti-tumor effects through inactivating the PI3K/AKT/mTOR pathway." (PMID 34488535, 2021). "Activation of the PI3K/Akt/mTOR pathway, through PIK3CA amplifications, PIK3CA/PIK3R1/PIK3R2 mutations and PTEN mutations/loss of function, has also been linked to more aggressive EC tumor behavior." (PMID 34422646, 2021). "Combination of multiple PI3K/Akt/mTOR pathway inhibitors, targeting different steps, may suppress both proliferation and function of Treg cells and achieve better anti-tumor effects." (PMID 34177907, 2021). "Several AKT/mTOR inhibitors have been evaluated for use in preclinical or clinical tumor therapy." (PMID 34255431, 2021).
tumor (continued). "Metabolic reprogramming-mediated by mTOR complexes implicates in orchestrating the interaction of TME components, particularly immune cells and neoplastic cells, suggesting the crucial role of PI3K/Akt/mTOR in the determination of tumor development, progression as well as drug resistance." (PMID 35250965, 2021). "Thus, this study analyzes the anti-tumor effects of zotarolimus, an mTOR inhibitor, on HCT-116 cells and the synergistic effects of zotarolimus when combined with 5-FU." (PMID 34361836, 2021). "have found that oncogenic mTOR signaling recruits MDSCs to promote tumor initiation." (PMID 33897705, 2021). "Many target genes are widely involved in a variety of signaling pathways, such as the ERK (extracellular regulatory protein kinase) and Akt/mTOR signaling pathway, the Wnt/β-catenin pathway, and the Hippo signaling pathway, which are involved in the process of tumor occurrence and development." (PMID 34988073, 2021). "The enhancement of ER stress with heat shock protein 90 (HSP90) inhibitors coupled with inhibitors of mechanistic target of rapamycin protein (mTOR) led to tumor shrinkage in a genetically engineered murine MPNST model, which correlated with profound ER damage and cell death." (PMID 34502310, 2021). "Both protocols were unable to prevent tumor-induced body weight loss; however, the study attributed therapeutic value only to AET, since it marginally rescued muscle mass and preserved function through restoration of the expression levels of mTOR." (PMID 35008195, 2021). "Fuchs and Bode hypothesized that LAT1 provides essential amino acids for tumor growth and proliferation and is overexpressed in cancer tissues via the mTOR signaling pathway, whereas SLC1A5 drives the function of SLC7A5 through glutamine delivery." (PMID 33783998, 2021). "Based on these observations, we deduced that Survivin might regulate the expression of P-gp through the PI3K/Akt/mTOR pathway, thereby playing a role in the chemotherapy resistance of tumor cells." (PMID 35047507, 2021). "For example, opioids, which are widely utilized in perioperative clinical practice for analgesia, could, after binding to their receptors (i.e., μ-opioid receptor), activate Akt and mTOR signaling, a well-defined pathway that contributes to tumor survival." (PMID 34631520, 2021). "In conclusion, the data of this study suggested that SCRAR5 was a potential tumor suppressor by regulating tumor growth and metastasis in CRC, which might be associated with PI3K/AKT/mTOR signaling pathway." (PMID 34417976, 2021). "Therefore, this study used the mutation, expression, and clinical data from the TCGA database to analyze the CNV, SNV, and gene expression status of mTOR signaling pathway genes in 33 tumors and the relationship between each tumor and patient prognosis." (PMID 34194607, 2021). "These agents mainly inhibit the mTOR pathway to prevent tumor progression." (PMID 34568017, 2021). "The AKT/mTOR signaling pathway plays an active role in promoting tumor invasion and metastasis." (PMID 35047403, 2021). "In this study, we found that mTOR was highly expressed in CRC patient tumor tissues and cells." (PMID 33946531, 2021). "Excessive activation of mTOR (mammalian target of rapamycin), a serine/threonine kinase, is associated with the activation of hypoxia inducible factor (HIF) that regulates angiogenesis and tumor growth." (PMID 34305611, 2021). "PI3K/AKT/mTOR pathway has been considered as a prospective target for tumor therapy." (PMID 34488535, 2021). "However, under conditions when tumor microvascular endothelial cells in culture are exposed to glucose starvation, metformin inhibits autophagy via inhibition of the mTOR pathway and a partially AMPK-independent mechanism in." (PMID 34421827, 2021).
tumor (continued). "Our research is focused on the hypothesis that autophagy plays a key role in the development of tumor resistance to everolimus, and that chloroquine addition to an mTOR inhibitor increases their inhibitory effect on tumor growth." (PMID 34944946, 2021). "Therefore, mTOR hyperactivity provides stabilization of HIF1α protein and other regulatory failures contributing to the HIF1α stabilization in pseudohypoxic tumor tissues." (PMID 34257622, 2021). "Each compound enhanced the phosphorylation of adenosine monophosphate-activated protein kinase (AMPK) by attenuating the phosphoinositide 3-kinase (PI3K)/protein kinase B (Akt)/mammalian target of rapamycin (mTOR) pathway, resulting in strong inhibition of benign tumor cell proliferation." (PMID 34445273, 2021). "These disappointing clinical results may also be due to mutations in tumour suppressor genes, and the abnormal expression of survival signalling factors involved in the PI3K/AKT/mTOR and/or MAPK/ERK signalling pathways." (PMID 33507584, 2021). "Given the critical role of the PI3K/AKT/mTOR axis in tumorigenesis and chemoresistance, we hypothesized that PRKAR1B-AS2 induces its tumor-promoting action by regulating PI3K/AKT/mTOR circuitry." (PMID 33668685, 2021). "In TME, mTOR activity in a subset of cells within the tumor mass can mediate MDSC accumulation." (PMID 33897705, 2021). "In addition, both the PI3K/AKT/mTOR and AKT/mTOR axes are reported to be involved in enhancing glycolysis in tumor cells and TAMs, which, in turn, promotes tumor cell survival and proliferation." (PMID 34900687, 2021). "Proteolytic stability of HMGCR may also be negatively regulated by adenosine monophosphate-activated protein kinase (AMPK), with its activity being closely correlated with tumor suppression when AMPK modulates mTOR and Akt pathways." (PMID 34440098, 2021). "Moreover, overexpression of TFG rescued the tumor‐suppressive effect and inhibition of the TGF‐β and AKT/mTOR signaling pathways caused by the down‐regulation of CLTC." (PMID 34185412, 2021). "In addition to having a directly positive effect against DMG cells, targeting of macrophage mTOR activity with rapamycin has been shown to stimulate macrophages towards an M1 phenotype, contributing to an overall anti-tumour effect within the setting of GBMs." (PMID 34944870, 2021). "Besides, resveratrol blocks glucose uptake in various tumor cells by inhibiting the cell membrane transport of Glut1 via the Akt/mTOR-dependent signaling pathway." (PMID 33430318, 2021). "PI3K/AKT/mTOR inhibition may decrease tumor cell proliferation, and enhance tumor immune surveillance by the secretion of immunosuppressive cytokines, the recruitment of intratumoral MDSCs, and the development of memory T cells." (PMID 34830179, 2021). "Interestingly, it was previously shown that mTOR inhibitors also increase Tregs, which dampens their anti-tumor response." (PMID 33802831, 2021). "It is noteworthy, however, that we observed more frequently increased values of total AKT in high-grade disease, while its enhanced expression was independently predictive of a poor OS and DSS, pointing to the involvement of the PI3K/mTOR/AKT pathway in tumor cell survival and disease progression." (PMID 34066040, 2021). "In the siRNA screen for RAS effector signaling networks, the RSK-mTOR pathway-activated tumor cells showed increased activation of mTOR signaling that negatively regulated autophagy, instead elevating oxidative phosphorylation and mitochondrial ribosome maintenance." (PMID 34680229, 2021). "Moreover, activation of the mammalian target of rapamycin (mTOR) pathway in microglia promoted tumor growth and immune evasion in murine GBM." (PMID 34094969, 2021). "mTOR, GβL and Rictor constitute an important signalling pathway in the regulation of tumour growth." (PMID 33523588, 2021).
tumor (continued). "Phosphorylation of FAK is needed for its kinase activity to induce downstream signals activation such as AKT and mTOR, and trigger various signaling pathways such as PI3K/AKT/mTOR signal pathway, MAPK6/ERK pathway, which was linked to aggressive tumor behaviors." (PMID 35201437, 2021). "In addition to the autophagy pathway, other negatively correlated pathways such as AMPK signaling, mTOR signaling, and spliceosome are involved in tumor cell progression." (PMID 33916291, 2021). "Thus, the inhibition of LAT1 means the suppression of mTOR signaling, and subsequently, the prevention of tumor growth." (PMID 34287243, 2021). "The mechanistic target of rapamycin (mTOR) is one of the main markers of tumor growth." (PMID 34771718, 2021). "GSEA suggested that various signaling pathways closely related to tumor occurrence and development (e.g., mTOR signaling pathway, WNT signaling pathway, VEGF signaling pathway, and NOTCH signaling pathway) were differentially enriched in those with the high COPB2 expression phenotype." (PMID 33824874, 2021). "In addition, the AKT/mTOR pathway is related to radiation resistance in tumor cells and activates not only DNA-PK to enhance DNA damage repair but also NF-κB to inhibit apoptosis." (PMID 34224316, 2021). "High expression of mTOR in our cohort was also associated with advanced tumor stage but not with any other analyzed parameter." (PMID 34833123, 2021). "However, in an MCF-7-implanted nude mouse model, it was possible to detect significantly decreased tumour volumes and tumour weights and decreased p-Akt and p-mTOR protein expression in the celastrol+tamoxifen group." (PMID 34337076, 2021). "Some hypotheses suggest that Merlin can inhibit cell proliferation with a contact-dependent regulation including Hippo, Notch and Patched pathway and that it can activate the mammalian target of rapamycin (mTOR) pathway during tumor development." (PMID 34679551, 2021). "Tumor development and angiogenesis have been noticed in many in vitro cell lines and in vivo murine xenograft models because of certain oncogene stimulation or failure of tumor suppressors genes that results into anomalous activation of mTOR pathway." (PMID 34535145, 2021). "Moreover, STAT3 signalling and mTOR signalling in lymphatic endothelial cells (LECs) within the PMN facilitate tumour cell extravasation and colonization." (PMID 35006432, 2021). "AMPK is considered a tumour suppressor, since it inhibits the mTOR pathway." (PMID 34572020, 2021). "GSEA results showed the enrichment of high THUMPD1 expression in mTOR signaling pathway, neurotrophin signaling pathway and phosphotidylinositol signaling system, which all stimulate aberrant cell metabolism, angiogenesis and malignant progression of tumor." (PMID 34762107, 2021). "Given the anti-tumor effect of puerarin on PDAC by inhibiting mTOR signal transduction, we next investigated whether activated mTOR signal transduction influenced this effect of puerarin." (PMID 34863080, 2021). "Low-dose triple combination of inhibitors reduced kinase activity in both PI3K/AKT/mTOR and mitogen-activated protein kinase pathways, inhibited proliferation in vitro, and significantly reduced tumor growth in PDX models, suggesting this combination merits further clinical exploration." (PMID 35582310, 2021). "Akt-mTor signaling has a critical role in tumor cell growth and survival." (PMID 34511602, 2021). "Therefore, mTOR inhibitors can synergistically inhibit tumor growth in combination with HSP90 inhibitors or AR inhibitors." (PMID 32175074, 2020). "PGAM1 silencing inhibits mTOR‐dependent glycolysis, cell proliferation, and tumor formation." (PMID 32167655, 2020). "Among all, the PI3K/AKT/mTOR pathway is particularly interesting because it is constitutively activated in a significant proportion of patients with HCC and it is associated with a more aggressive tumor progression and shorter survival." (PMID 32070029, 2020).